SHOX2 (SHOX homeobox 2)
Diseases named in the same sentence as SHOX2 in open-access papers (continued):
Sharing a sentence is not in itself a finding about the gene and the disease.
Bradycardia (4 papers, 2013 to 2021). A slower than normal heart rate (in adults, slower than 60 beats per minute). "SHOX2 is considered as a key regulator of sinus node development of which deficiency could lead to bradycardia in animal models." (PMID 32226785, 2020). "In addition, deficiency of both Isl1 and Shox2 in fish, as well as Shox2 deficiency in the mouse results in a bradycardia phenotype." (PMID 23455426, 2013). "Examination of knockout embryos from a 250-kb deletion mouse line at the Shox2 locus showed loss of Shox2 expression in the SAN, with dysregulation of Shox2 target genes, hypoplasia of the SAN, and embryonic lethality presumed due to bradycardia." (PMID 34335313, 2021). "In the mouse, the homozygous loss of Shox2 results in embryonic lethality with bradycardia, whereas heterozygous mice have not yet been studied in much detail." (PMID 27138930, 2016).
gastric adenocarcinoma (4 papers, 2021 to 2022). "Overexpressed IGF2-AS is confirmed in gastric adenocarcinoma tissues which exhibits a great functional role in promoting cancer cell progression by sponging miR-503 as a ceRNA to regulate SHOX2 expression." (PMID 35693981, 2022). "The up‐regulation of IGF2‐AS promotes metastasis of gastric adenocarcinoma via serving as an endogenous sponge of miR‐503 to elevate SHOX2 expression." (PMID 34427967, 2021).
lymph node metastasis (4 papers, 2020 to 2025). "SHOX2 expression was higher in subtypes prone to lymph node metastasis, prone to recurrence, with poor differentiation, and with poor prognosis." (PMID 34262939, 2021).
adenoma (3 papers, 2016 to 2025). A neoplasm arising from the epithelium. "In correlation to the stepwise increase of SEPT9 and SHOX2 methylation level, the adenoma group was evaluated for other characteristics with known potential for supporting a malignant transition." (PMID 27660666, 2016). "ROC analyses showed that SHOX2 hypermethylation was able to discriminate between CRC vs. controls (AUC = 0.88, 95 % CI = 0.77–0.99, p < 0.001) and adenomas vs. controls (AUC = 0.90, 95 % CI = 0.85–0.95, p < 0.001)." (PMID 27660666, 2016). "ROC analyses showed that SHOX2 hypermethylation was able to discriminate between CRC vs. controls (AUC = 0.91, 95 % CI = 0.81–1.00, p < 0.001) and adenomas vs. controls (AUC = 0.88, 95 % CI = 0.82–0.94, p < 0.001)." (PMID 27660666, 2016). "Another methylation marker, SHOX2, was found to gradually increase in its levels from non-cancerous tissues to non-advanced adenomas, advanced adenomas, finally peaking in CRC cases." (PMID 36359889, 2022). "However, SHOX2 methylation assay failed in the differentiation between CRC and adenoma (AUC = 0.56, 95 % CI = 0.43–0.69, p = 0.33)." (PMID 27660666, 2016). "However, SHOX2 methylation assay failed in the differentiation between CRC and adenoma (AUC = 0.60, 95 % CI = 0.48–0.74, p = 0.095)." (PMID 27660666, 2016). "Surprisingly, >50 % of SEPT9 Triplex methylation levels in CRC and adenomas showed a value exceeding 100 %, technically reasoned by a distant location of the reference gene (ACTB at chromosome 7) and the analyzed gene loci (SEPT9 gene at chromosome 17 and SHOX2 at chromosome 3q)." (PMID 27660666, 2016). "Adenomas showed a SHOX2 methylation level of 55.3 % ± 36.9 without separation in N-AA and AA." (PMID 27660666, 2016). "Adenomas showed a SHOX2 methylation level of 40.2 % ± 40.6 without separation in N-AA and AA." (PMID 27660666, 2016). "In conclusion, SEPT9 or SHOX2 methylation may be auxiliary biomarkers for the differentiation of CRC and advanced adenomas to non-advanced adenomas and normal tissue." (PMID 27660666, 2016). "Moreover, it was revealed that the assessment of promoter methylation of SEPT9 as well as SHOX2 may actually help distinguish CRC and adenomas from normal epithelium without dysplasia." (PMID 27660666, 2016).
cleft palate (3 papers, 2013 to 2016). Cleft palate is a fissure type embryopathy that affects the soft and hard palate to varying degrees. "Among these genes, ablation or mutation of Alx3, Lhx8, Pax3, Pitx1, Shox2, and Zeb2 induces cleft palates in humans and/or mice." (PMID 27329940, 2016). "We did not observe any obvious defects or malformations in the palate of Nestin-Cre; Shox2flox/− mutant pups, suggesting that the absence of milk in Shox2-mutant neonatal stomachs was not due to cleft palate malformations." (PMID 26156498, 2015).
head and neck squamous cell carcinoma (3 papers, 2018 to 2021). A squamous cell carcinoma that arises from any of the following anatomic sites: lip and oral cavity, nasal cavity, paranasal sinuses, pharynx, larynx, and salivary glands. "The same phenomenon has been reported for methylated TAC1 promoter DNA for esophageal squamous cell carcinoma, SHOX2 and SEPT9 for head and neck squamous cell carcinomas." (PMID 30849971, 2019).
hepatocellular carcinoma (3 papers, 2021 to 2023). A malignant tumor that arises from hepatocytes. "As evidenced by the observation that the expression level of SHOX2 was closely related to cancer recurrence in hepatocellular carcinoma (HCC), SHOX2 might play a significant role in tumorigenesis." (PMID 37170390, 2023). "Besides this, elevated SHOX2 expression correlates with tumor recurrence in hepatocellular carcinoma." (PMID 34465361, 2021).
lung disease (3 papers, 2014 to 2021). "DNA methylation of the short stature homeobox 2 (SHOX2) gene was found to be a diagnostic clinical biomarker candidate for the detection of malignant lung disease even in patients where histology and cytology results are equivocal." (PMID 25229548, 2014). "For example, DNA methylation of SHOX2 was exploited as an effective biomarker to distinguish between malignant lung disease and controls with a relative high sensitivity." (PMID 31894857, 2020).
papillary thyroid cancer (3 papers, 2013 to 2018). "All the genes except SHOX2 showed dense methylation in at least one papillary thyroid cancer cell line, confirming that hypermethylation detected in cancer tissue samples is due to hypermethylation in cancer cells." (PMID 24367375, 2013). "Merely 36% of papillary thyroid carcinomas were found to be methylated at the SHOX2 locus." (PMID 27999621, 2016). "Kikuchi et al26 identified multiple genes (HIST1H3J, POU4F2, SHOX2, PHKG2, TLX3 and HOXA7) with frequent epigenetic hypermethylation in papillary thyroid cancer, which might function as potential biomarkers." (PMID 30039914, 2018).
small cell lung carcinoma (3 papers, 2019 to 2021). Small cell lung cancer (SCLC) is a highly aggressive malignant neoplasm, accounting for 10-15% of lung cancer cases, characterized byrapid growth, and early metastasis. "However, the results also indicate that SHOX2 gene methylation exhibits lower sensitivity for stage I tumors, and the sensitivity to small cell lung cancer (SCLC) and squamous cell carcinoma (SCC) is higher than that of adenocarcinoma (Adenoca)." (PMID 33425721, 2020).
acute myeloid leukemia (2 papers, 2021 to 2023). Acute myeloid leukemia (AML) is a group of neoplasms arising from precursor cells committed to the myeloid cell-line differentiation. "However, SHOX2 mRNA expression was lower in breast invasive carcinoma (BRCA), acute myeloid leukemia (LAML), testicular germ cell tumors (TGCT), skin cutaneous melanoma (SKCM) and thyroid carcinoma (THCA)." (PMID 37170390, 2023). "In addition, lower SHOX2 expression was observed in breast invasive carcinoma (BRCA), acute myeloid leukemia (LAML), and testicular germ cell tumors (TGCTs)." (PMID 34262939, 2021).
Ascites (2 papers, 2016 to 2025). Accumulation of fluid in the peritoneal cavity (between the layers of the peritoneum that lines the abdomen). "Ascites was evaluated by means of cytopathological investigation and DNA methylation of SHOX2 and SEPT9 in the cell-free and cellular fraction." (PMID 26937257, 2016). "The DNA methylation biomarkers SHOX2 and SEPT9 are of diagnostic and prognostic value in ascites." (PMID 26937257, 2016). "It was suggested that SHOX2, SEPTIN9 and four-gene methylation combined detection were important factors affecting the prognosis of patients with ascites." (PMID 41477641, 2025). "The analysis indicated that methylation of SHOX2 and SEPTIN9 were independent factors affecting the prognosis of patients with ascites." (PMID 41477641, 2025). "The methylation status of SHOX2 and SEPTIN9 genes is significantly correlated with the prognosis of patients with ascites." (PMID 41477641, 2025). "Thus, the capability of SHOX2 and SEPT9 methylation to distinguish between malignant and paramalignant ascites was evaluated in a subgroup of cancer patients by comparing the survival in positive versus negative patients." (PMID 26937257, 2016).
congenital heart disease (2 papers, 2013 to 2019). A heart disease that is present at birth. "Moreover, SHOX2 is implicated in specifying neural systems involved in processing somatosensory information, as well as in face and body structure formation and has been reported as involved in Cornelia de Lange syndrome—a condition that implies heart defects." (PMID 31480262, 2019). "While genetic variation in ISL1 is associated with congenital heart disease and cardiomyopathies, SHOX2 has not been linked to any human phenotype yet." (PMID 23455426, 2013).
heart failure (2 papers, 2014 to 2020). Inability of the heart to pump blood at an adequate rate to meet tissue metabolic requirements. "Given that Shox2 participates in heart development as shown by different knockout mice models, it is tempting to speculate that Shox2 also regulates Nppb expression in heart and that the disruption of this pathway is critical for the heart failure in Shox2 knockout mice models." (PMID 24421874, 2014). "In the heart failure mice, qPCR showed no significant change in Bmp2, Bmp4, Nkx2.5, Shox2 and Tbx3 in the sinus node, but there was a significant downregulation of Tbx18 and Isl1 and upregulation of AP1, Mef2c and NRSF mRNA." (PMID 32647133, 2020).
Obesity (2 papers, 2020 to 2024). Accumulation of substantial excess body fat. "In particular, there is clear evidence for depot specific expression of developmental genes like Short Stature Homeobox 2 (Shox2), T-Box 15 (Tbx15), Engrailed 1 (En1), and Homeobox-genes (e.g., Hoxa5, Hoxc8, and Hoxc9) which have been suggested to play a role in the origin of obesity and body FD." (PMID 32273869, 2020).
ovarian carcinoma (2 papers, 2016 to 2023). A malignant neoplasm originating from the surface ovarian epithelium. "Methylation of SHOX2 or SEPT9 was detected in ascites samples of patients suffering from different malignancy entities including, among others, ovarian cancer, hepatic or pancreatic cancer, gallbladder or bile duct cancer, and non-Hodgkin lymphoma." (PMID 26937257, 2016).
renal cell carcinoma (2 papers, 2021 to 2025). "In addition, the PRAT browning process has been specifically detected in renal cell carcinoma (RCC), being characterized by upregulated expression of brown/beige adipocytes markers (UCP1, PPAR-ɣ, c/EBPα, and PGC1α) and downregulated white fat cells markers, such as LEPTIN, SHOX2, HOXC8, and HOXC9." (PMID 40227577, 2025).
Turner syndrome (2 papers, 2013 to 2017). Turner syndrome is a chromosomal disorder associated with the complete or partial absence of an X chromosome. "SHOX2, a gene which codes for Short stature homeobox protein 2, is a transcriptional factor involved in various embryological development processes, and is implicated in Turner syndrome, whereby gene knockout of SHOX2 in mice results in skeletal growth abnormalities and short stature phenotypes." (PMID 28828235, 2017). "SHOX2 is a member of the homeobox gene family, and is reported to relate to a short-stature phenotype of Turner syndrome." (PMID 24367375, 2013).
abscesses (1 paper, 2010). "DNA methylation of SHOX2 allowed to distinguish between malignant and benign lung disease, i.e. abscesses, infections, obstructive lung diseases, sarcoidosis, scleroderma, stenoses, at high specificity (68% sensitivity [95% CI 62-73%], 95% specificity [95% CI 91-97%])." (PMID 21047392, 2010).
adenoid cystic carcinoma (1 paper, 2023). A malignant tumor arising from the epithelial cells. "In addition, four of the other five MPE patients were positive, with single positivity for SHOX2 in ovarian and thymic squamous cell carcinoma and double positivity for SHOX2 and RASSF1A in lymphoma and adenoid cystic carcinoma." (PMID 36691467, 2023).
ankylosis (1 paper, 2014). Fixation and immobility of a joint. "Our previous study reported that inactivation of Shox2 led to dysplasia and ankylosis of the temporomandibular joint (TMJ), and that replacing Shox2 with human Shox partially rescued the phenotype with a prematurely worn out articular disc." (PMID 25062348, 2014). "Previous reports showed that targeted inactivation of Shox2 leads to severe defects in a number of developing organs including heart, palate, and limb, and that TMJ exhibits dysplasia and ankylosis in mice." (PMID 25062348, 2014). "Previous reports show that tissue-specific inactivation of Shox2 in the cranial neural crest cells leads to TMJ dysplasia and ankylosis, accompanied by significant down-regulation of Sox9, Runx2 and Ihh." (PMID 25062348, 2014).
biliary tract cancer (1 paper, 2016). "Thus, a larger study cohort, possibly based on a multicenter approach in a prospective fashion, is needed to more precisely assess the potential of SHOX2 and SEPT9 methylation as a biomarker for all four subgroups of biliary tract cancer." (PMID 27999621, 2016). "SHOX2 and SEPT9 are frequently methylated in biliary tract cancers." (PMID 27999621, 2016).
breast tumors (1 paper, 2021). "The impact of SHOX2 signaling on tumor growth and metastasis was evaluated in orthotopic breast tumor mice." (PMID 34465361, 2021). "This worse prognostic feature of high SHOX2 expression also corresponded with ER negative (ER−) breast tumors having overall higher SHOX2 expression than ER positive (ER+) breast tumors (p < 0.0001)." (PMID 34465361, 2021).
cholangiocarcinoma (1 paper, 2016). A carcinoma that arises from the intrahepatic biliary tree (intrahepatic cholangiocarcinoma) or from the junction, or adjacent to the junction, of the right and left hepatic ducts (hilar cholangiocarcinoma). "SHOX2 and SEPT9 methylation as a marker panel achieved a sensitivity of 45% and a specificity of 99% in differentiating between samples from patients with and without cholangiocarcinoma (AUC = 0.752; 95% CI 0.631–0.873)." (PMID 27999621, 2016). "Relative DNA methylation of SHOX2 and SEPT9 was quantified in tumor specimens and matched normal adjacent tissue (NAT) from 71 BTC patients, as well as in plasma samples from an independent prospective cohort of 20 cholangiocarcinoma patients and 100 control patients." (PMID 27999621, 2016).
colorectal tumors (1 paper, 2023). "SHOX2 has been relatively poorly studied regarding the diagnosis of CRC, but one study has reported that SHOX2 methylation levels were significantly higher in colorectal tumors than in normal tissue." (PMID 36803423, 2023).
developmental delay (1 paper, 2011). "They reason that, as none of their patients had congenital anomalies apart from their skeletal features, and none had developmental delay, if SHOX acts outside of the musculo-skeletal system, its extra skeletal functions are redundant with other genes; perhaps SHOX2 or other HOX genes." (PMID 21731768, 2011).
endometriosis (1 paper, 2021). The growth of functional endometrial tissue in anatomic sites outside the uterine body. "EN1, PITX3, and SHOX2 are involved in neuron formation in eutopic and ectopic tissues, and the altered expressions in these genes may be related to nerve formation and pain sensation in endometriosis patients." (PMID 34470627, 2021).
epithelial dysplasia (1 paper, 2016). "Correspondingly, the highest grade of epithelial dysplasia (D1-3) is correlated with significantly higher methylation of SEPT9 (ρ = 0.24, p = 0.047), but not of SHOX2 (ρ = −0.06, p = 0.58)." (PMID 27660666, 2016). "The highest grade of epithelial dysplasia (D1-3) showed a trend of higher methylation of SEPT9 (ρ = 0.23, p = 0.056), but not of SHOX2 (ρ = −0.06, p = 0.60)." (PMID 27660666, 2016).
familial atrial fibrillation (1 paper, 2022). An autosomal dominant heart condition that causes disruptions in the heart's normal rhythm. "In humans, mutations that disrupt SHOX2 function also affect heart rhythm and are inherited as familial atrial fibrillation." (PMID 35740984, 2022).
glioblastoma (1 paper, 2021). The most malignant astrocytic tumor (WHO grade IV). "Higher SHOX2 expression was observed in glioblastoma (GBM), HNSC, and LUSC." (PMID 34262939, 2021).
metastatic disease (1 paper, 2022). "SEPT9 and SHOX2 ccfDNA methylation allowed distinguishing patients with localized and metastatic disease (p < 0.001 for both)." (PMID 36139516, 2022).
Paralysis (1 paper, 2015). Paralysis of voluntary muscles means loss of contraction due to interruption of one or more motor pathways from the brain to the muscle fibers. "Given that the face of Shox2-mutant neonates are severely devoid of innervation, the behavioral abnormalities exhibited by Shox2-mutant animals could be attributed to facial paralysis." (PMID 26156498, 2015). "Furthermore, we demonstrate that Shox2-mutant neonates display impaired feeding behavior, perhaps due to facial paralysis as a result of improper development and function of the facial nerves." (PMID 26156498, 2015). "If regionally restricted loss of Shox2 in facial motor nucleus does not result in postnatal lethality, future studies could examine Shox2-mutant behavior later postnatally and in the adult to test whether Shox2-mutant animals have control over their face or are experiencing facial paralysis." (PMID 26156498, 2015).
polycystic kidney disease (1 paper, 2009). A usually autosomal dominant and less frequently autosomal recessive genetic disorder characterized by the presence of numerous cysts in the kidneys leading to end-stage renal failure. "A mouse knock-out of Wwtr1 displays a phenotype resembling human polycystic kidney disease, and the mouse knock-out of Shox2 is lethal with cleft palate, strongly suggesting that these genes are linked to human disease, although neither is annotated as a disease gene in OMIM." (PMID 19909546, 2009).
Tremor (1 paper, 2015). An unintentional, oscillating to-and-fro muscle movement about a joint axis. "Nestin-Cre; Shox2flox/− mutant pups also displayed tremors 16–26 h following birth, which could be related to defects in neural circuitry or result from a loss of Shox2 function in other regions of the hindbrain." (PMID 26156498, 2015).